RNU6-603P (RNA, U6 small nuclear 603, pseudogene)
Synonyms: RNU6-825P
Gene: Small nuclear RNA gene on chromosome 6 (32,352,877 to 32,352,983, forward strand). Ensembl gene ENSG00000223335.
Homologues: Orthologues: chimpanzee U6 (98% identical), guinea pig U6 (63% identical), mouse Gm24631 (57% identical). Paralogues in human: RNU6-1091P (80% identical), RNU6-1083P (79% identical), RNU6-445P (79% identical), RNU6-727P (79% identical), RNU6-797P (79% identical), RNU6-1152P (79% identical), RNU6-1218P (79% identical), RNU6-1243P (79% identical), RNU6-1287P (79% identical), RNU6-1309P (79% identical), RNU6-272P (79% identical), RNU6-364P (79% identical), and 1285 more.